FMR1 (fragile X messenger ribonucleoprotein 1)
Diseases named in the same sentence as FMR1 in open-access papers (continued):
Sharing a sentence is not in itself a finding about the gene and the disease.
fragile X syndrome (continued). "In Fmr1-knockout (KO) mice—a model for fragile X syndrome—the protein levels of several FMRP targets are increased in PSD fractions either from the neocortex or hippocampus, including Sapap1–3, Shank1, Shank3, and various glutamate receptor subunits." (PMID 36497075, 2022). "For instance, the Cas9-mediated DNA methylation editing of FMR1 efficiently repairs neuronal abnormalities observed in fragile X syndrome (FXS)." (PMID 36109806, 2022). "Methylation near a disease-implicated repeat region was first reported in Fragile X Syndrome, a trinucleotide repeat disease involving a CGG expansion in the 5′-UTR of the fragile X mental retardation I (FMR1) gene." (PMID 35592702, 2022). "An augmented number of dysmorphogenetic dendritic spines is a consistent feature of a common inherited cause of ID, the fragile X syndrome (FXS), characterized by mutations of the FMRP, the protein encoded by the FMR1 gene." (PMID 34216332, 2022). "For instance, Fmr1 KO mice (Fragile X syndrome) showed impaired microglia-mediated synaptic elimination during the developmental period in CA region of the brain." (PMID 35693812, 2022). "We successfully demonstrate the applicability of this approach by examining the properties of hippocampal spines in juvenile Fmr1 KO mice, a mouse model of Fragile X Syndrome." (PMID 36359212, 2022). "The CGG repetitive region in the promotor of the fragile mental retardation protein translational regulator (FMR1) gene, when expanded to over 200 triplets (full mutation), leads to methylation and gene silencing and, consequently, Fragile X syndrome (FXS; OMIM #3000624)." (PMID 35327973, 2022). "FMR1 expansions were detected in nine boys and one girl, and a diagnosis of Fragile X syndrome fully or partially explained the presenting clinical features (patients 59–68)." (PMID 35182509, 2022). "The loss of the FMR1 protein can cause fragile X syndrome (FXS) and other diseases." (PMID 36347844, 2022). "The mouse model that has been typically used to study Fragile X syndrome is a knockout of the Fmr1 gene." (PMID 35977823, 2022). "Preserving the health of mothers with the FMR1 premutation as they age is important for both the outcomes of the mothers and for their children with fragile X syndrome." (PMID 35026985, 2022). "The utility of this system to study neurodevelopmental disorders was validated by examining spine development in fmr1 mutant zebrafish, a model of fragile X syndrome." (PMID 35875841, 2022). "Fibre labelling of individual replication forks in the CGG-expanded FMR1 locus from Fragile X syndrome cells revealed stalling." (PMID 35853874, 2022). "A recent study showed that miR-129 negatively regulates neuronal migration by targeting Fmr1 mRNA which are transcripts of Fragile X syndrome gene Fmr1." (PMID 36291300, 2022). "PAK2 is important for brain development, and its haploinsufficiency leads to autism-related behavior and its inhibition partially restores several synaptic fragile X syndrome phenotypes in the Fmr1 KO mice." (PMID 36292679, 2022). "Fragile X syndrome (FXS), the most prevalent X-linked monogenic cause of ID/ASD, is characterized by homozygous null FMR1 mutations and epileptic seizures." (PMID 36142719, 2022).
fragile X syndrome (continued). "For example, the RNA-binding protein FMRP, encoded by the FMR1 gene, inhibits translation initiation and mutations in the gene causes the Fragile X Syndrome (FXS), the most common inherited cause of ASD." (PMID 34659781, 2021). "Forexample, the expansion of CGG trinucleotide repeats in the5′-untranslated region (5′-UTR) of the FMR1 gene, associatedwith the fragile X syndrome, disrupts the structure of TAD,that includes FMR1." (PMID 34541447, 2021). "Of note, the gene fragile X mental retardation 1 (Fmr1, the gene primarily disrupted in fragile X syndrome) is an important regulator of local mRNA translation in dendrites." (PMID 34360985, 2021). "One such classic example is an expanded STR in the promoter region of FMR1, seen in Fragile X syndrome (FXS)." (PMID 34034831, 2021). "Fragile X syndrome results from a CGC repeat in the 5′ untranslated region of the FMR1 gene and affects approximately 1 in 4,000 males and 1 in 6,000 females." (PMID 33184995, 2021). "For instance, in Fragile X syndrome patients and Fmr1 knockout mice, the number of dendritic spines in mature cortical neurons was increased because of the deficit in MEF2-dependent synapse elimination." (PMID 34262438, 2021). "Using the Fmr1 knockout mice to mimic the fragile X syndrome, authors observed that pharmacological blockade of CB1R rescued several pathological alterations, including the increased susceptibility to AS." (PMID 33643007, 2021). "Fragile X syndrome, which is a leading form of ASD, is caused by mutation in the promoter region of the fragile X mental retardation 1 gene (FMR1)." (PMID 33420078, 2021). "The fragile X mental retardation 1 (FMR1) gene contains CGG repeats that can expand to >200 copies (full mutation), causing fragile X syndrome, a condition frequently co-diagnosed with autism and other intellectual disabilities." (PMID 34070950, 2021). "FMR1-related disorders include fragile X syndrome (FXS), fragile X tremor/ataxia syndrome (FXTAS), and premature ovarian insufficiency (POI), and result from expansion of the trinucleotide CGG repeat in the 5′ untranslated region." (PMID 34356138, 2021). "Dysfunction of both FMR1 and UBE3A are known to cause syndromic forms of ID, fragile X syndrome (OMIM: 300624) and Angelman syndrome (OMIM: 105830) respectively." (PMID 33758288, 2021). "One of the arguments for using this route is that in Fmr1-/- mice (an animal model of Fragile X syndrome), learning and memory impairments were ameliorated by intranasal IGF-2." (PMID 33673334, 2021). "We also tested Straglr’s ability to detect mosaicism using simulated fragile X syndrome (FXS) samples that contained different relative abundances of a premutation (PM, 150 repeats) and full mutation (FM, 500 repeats) FMR1 expansions." (PMID 34389037, 2021). "One preclinical study aiming to identify a novel treatment for Fragile X syndrome used a directed DNA demethylation tool to remove methylation marks in the FMR1 promoter region, leading to increased FMR1 expression." (PMID 34322133, 2021). "ANS dysfunction has also been implicated in fragile X syndrome (FXS), a monogenic disorder cause by a CGG trinucleotide expansion mutation on the FMR1 gene on the X chromosome." (PMID 34690833, 2021). "Thus, the lower FMRP expression detected in individuals with a full mutation and mosaicism and in individuals carrying a premutation allele could be responsible for the clinical, cognitive, and behavioral impairment seen in fragile X syndrome and FMR1 associated disorders." (PMID 34679478, 2021). "Highly congruent to ASD are the alternative splicing changes recently identified in the hippocampus from the Fragile X Syndrome mouse model [Fmr1 knockout (KO)]." (PMID 34566717, 2021).
fragile X syndrome (continued). "Consistent with the clinical findings in patients with fragile X syndrome, fmr-1 knock out mice exhibited higher gamma power within the auditory and frontal cortex, an effect exacerbated when the animals were in motion." (PMID 34887388, 2021). "Similar deficits are also observed in fragile X syndrome (FXS), a single-gene disorder caused by a mutation in the FMR1 gene and the most common single-gene disorder associated with ASD." (PMID 34819882, 2021). "For example, the anomalous rise of rho GTPase Rac1 activity inhibited cofilin in mice with Fragile X syndrome because of a trinucleotide expansion in the FMR1 gene on the X chromosome." (PMID 34194309, 2021). "Fragile X syndrome typically originates from the dynamic expansion of CGG trinucleotide repeats found in the 5′ UTR of the FMR1 gene (Xq27.3)." (PMID 34068266, 2021). "Fragile X syndrome (FXS) is a neurodevelopmental disorder, characterized by intellectual disability and sensory deficits, caused by epigenetic silencing of the FMR1 gene and subsequent loss of its protein product, fragile X mental retardation protein (FMRP)." (PMID 33993189, 2021). "Our final demethylation target was the FMR1 gene which, in patients with Fragile X syndrome, undergoes a CGG repeat expansion (>200 repeats) in its 5′ UTR that becomes aberrantly hypermethylated and results in silencing of FMR1 transcription." (PMID 34588447, 2021). "This work has focused on Fragile X syndrome, where a trinucleotide repeat (CGG) expansion mutation in FMR1 causes reduction or loss of expression of FMRP, which normally serves to repress mGluR5-activated mRNA translation." (PMID 32939596, 2021). "Fragile X Syndrome (FXS) is a leading inherited cause of autism and intellectual disability, resulting from a mutation in the FMR1 gene and subsequent loss of its protein product FMRP." (PMID 35069112, 2021). "Here, we have investigated the development of AMPAR-mediated synaptic transmission in the hippocampus of the Fmr1 knock-out (KO) mouse, a widely used model of Fragile X syndrome (FXS)." (PMID 33343326, 2020). "Expansion of the CGG triplet in the FMR1 gene (>200 repeats for complete penetrance) is attributed as the main cause of Fragile X syndrome (FXS), and in a pre-mutation state (55–200 repeats) is responsible for Fragile X-Associated Tremor/Ataxia Syndrome (FXTAS)." (PMID 32435641, 2020). "The full mutation of the FMR1 gene contains >200 CGG repeats and this causes fragile X syndrome (FXS), the most common inherited cause of intellectual disability and the most common single gene cause of autism spectrum disorder." (PMID 33133171, 2020). "One widely studied specific sex chromosome alteration that has been associated with neuropsychiatric conditions is Fragile X syndrome (FXS), which is caused by the expansion of a trinucleotide repeat in the Fragile X Mental Retardation 1 (FMR1) gene on the X chromosome." (PMID 32348611, 2020). "Mutations of the activity-dependent RNA-binding protein FMRP, encoded by the FMR1 gene found on the X chromosome, cause Fragile X syndrome, a disorder associating ID and ASD." (PMID 32982715, 2020). "Fragile X syndrome (FXS), the most common monogenic form of autism, is caused by a loss of expression of the translational regulator FMRP, and FMR1 knockout mice provide a model for this disorder with good construct validity." (PMID 32793004, 2020). "Mutations of FMR1, which encodes FMRP, underlie the inherited intellectual disability Fragile X syndrome, which is the most common monogenic form of autism." (PMID 33375033, 2020). "Fragile X Syndrome (FXS) is a genetic cause of intellectual disability that results from a mutation in the Fragile X Mental Retardation 1 (Fmr1) gene and down-regulation of Fragile X Mental Retardation Protein (FMRP)." (PMID 32848552, 2020).
fragile X syndrome (continued). "Consistent with findings in brain tissue from Fragile X syndrome subjects, studies on L5 cortical neurons found that Fmr1 knockout mice display increased spine densities with immature, abnormally elongated, spine morphologies even at adult ages." (PMID 32982715, 2020). "For example, Fragile X syndrome (FXS) is a leading monogenic cause of ASD, driven by loss of the Fragile X Mental Retardation 1 (FMR1) gene." (PMID 32293529, 2020). "Some of the best-studied syndromic ASD genes are FMR1 (Fragile X syndrome), TSC (Tuberous sclerosis), and UBE3a (Angelman syndrome; Bourgeron, 2015; Sztainberg and Zoghbi, 2016)." (PMID 32982715, 2020). "In the fragile X mental retardation 1 knockout (Fmr1 KO) mouse model of Fragile X Syndrome, significantly increased levels of both sAPPα and ADAM10 are found at postnatal day 21 but not in adulthood." (PMID 33374371, 2020). "Using global proteomic analysis and a mouse model of fragile X syndrome, Fmr1 KO mice, this study reveals that the local production of mitochondrial proteins plays an essential role in synaptic functions." (PMID 32558077, 2020). "Fragile X syndrome (FXS) is a monogenic disorder caused by mutations in the FMR1 gene, which encodes fragile X mental retardation protein (FMRP)." (PMID 32788572, 2020). "Fragile X syndrome (FXS) is caused by a full mutation (FM, >200 CGGs) expansion in the promoter region of the FMR1 (fragile X mental retardation 1) gene." (PMID 33008014, 2020). "Typically, if the CGG repeat is below 200, it is unmethylated, but the majority of expanded CGG repeats over 200 are hypermethylated, leading to transcriptional silencing of FMR1 and fragile X syndrome." (PMID 31178126, 2019). "While there are many drug interventions that reduce behavioral deficits in Fmr1 mice and efforts to translate these preclinical breakthroughs into clinical trials for Fragile X Syndrome (FXS), evidence-based clinical interventions are almost non-existent." (PMID 31649514, 2019). "Numerous preclinical studies have supported the theory that enhanced activation of mGluR5 signaling, due to the absence or reduction of the FMR1 protein, contributes to cognitive and behavioral deficits in patients with fragile X syndrome (FXS)." (PMID 30653533, 2019). "Like in DM1, the unstable microsatellite in fragile X syndrome (FXS) is a non-coding repeat: A (CGG●CCG)n sequence in the 5′ UTR of FMR1 on the X-chromosome." (PMID 31357652, 2019). "Fragile X syndrome (FXS, OMIM 300624), one of the common forms of familial intellectual disability, is caused by CGG repeat expansion in the 5′-untranslated region of FMR1 gene on X chromosome." (PMID 31096929, 2019). "Attenuated sCPP has been demonstrated in genetic models of ASD such as in fmr1 mutant mice, a model for Fragile X syndrome, and BTBR T+tf/J (BTBR) mice." (PMID 31708750, 2019). "The second mechanism is through mutations that affect the expression of G-quadruplex binding proteins, as in the fragile X mental retardation 1 (FMR1) gene and Fragile X syndrome." (PMID 30322030, 2018). "Another well-characterized example is Fragile X syndrome, the most common developmental cause of mental retardation and a common cause of ASD, which results from the transcriptional silencing of the FMR1 gene." (PMID 30083288, 2018). "Fragile X syndrome is one of the most prevalent monogenic forms of ASD and is caused by the expansion of CGG repeats in the Fmr1 gene, which encodes the Fragile X Mental Retardation Protein." (PMID 30417082, 2018). "In the Fragile X syndrome genetic mouse model, elevated phosphorylation of GSK3β was found in the Fmr1 knockout mice, which suggests overactivation of Wnt signaling in this genetic ASD model." (PMID 30524240, 2018). "For example, patients with fragile X syndrome (FXS), caused by a silencing of the FMR1 gene, exhibit impairments in visual function specific to the dorsal system, which processes motion information." (PMID 29950161, 2018).
fragile X syndrome (continued). "This type of seizure, AGS, is also the representative phenotype of Fmr1-KO mice, a model of fragile X syndrome." (PMID 30333725, 2018). "These diseases, FRAXA (Fragile X syndrome), POF/POI (premature ovarian failure) and FXTAS (tremor/ataxia syndrome) are associated with a CGG repeats expansion, which is located at the FMR1 gene promoter region." (PMID 29986653, 2018). "The fragile X syndrome arises from the FMR1 CGG expansion of a premutation (55–200 repeats) to a full mutation allele (>200 repeats) and is the most frequent cause of inherited X-linked intellectual disability." (PMID 29868108, 2018). "Increased and decreased rates of SG dominance predict accurate, failed, and changed place memory in wild-type (WT) mice as well as cognitive inflexibility in a Fmr1-null mutant mouse model of Fragile X Syndrome (FXS) intellectual disability, which is associated with high prevalence of autism." (PMID 29346381, 2018). "A specific and direct involvement of Elavl1 (i.e., HuR antigen) has been shown in cases of Fragile X Syndrome, in which mutations in the 3′UTR of FMR1 abrogate a Elavl1/HuR binding site." (PMID 30687010, 2018). "Fragile X syndrome (FXS), the most common form of inherited intellectual disability (ID) and a leading cause of autism, results from the loss of expression of the Fmr1 gene which encodes the RNA-binding protein Fragile X Mental Retardation Protein (FMRP)." (PMID 30319351, 2018). "The aim of the article is to present the knowledge about the molecular background and epidemiology of fragile X syndrome and other FMR1-related disorders." (PMID 29641417, 2018). "In the fragile X syndrome, a monogenic form of autism spectrum disorder, the loss-of-function of FMRP encoded by the FMR1 gene leads to excessive translation of proteins, that would otherwise be rate-limiting for synaptic remodeling." (PMID 29456523, 2018). "The article presents the basic methods used in the molecular diagnosis of Fragile X syndrome and other FMR1-related disorders." (PMID 29641418, 2018). "Downregulation of tonic GABAergic inhibition was previously reported in subiculum and amygdala in Fmr1 KO mice, a mouse model of fragile X syndrome, which also exhibits autism-related behaviors." (PMID 28966979, 2017). "Fragile X syndrome is caused by the loss of function of Fmr1 due to the increased expansion and hypermethylation of trinucleotide (CGG) repeats within the promoter of Fmr1." (PMID 28882193, 2017). "CYFIP1 interacts with the Fragile X mental retardation protein (FMRP, encoded by the FMR1 gene), whose absence causes Fragile X syndrome, and with the translation initiation factor eIF4E." (PMID 28183735, 2017). "Here, we combined computational simulations with analysis of in vivo two-photon Ca2+ imaging data from somatosensory cortex of Fmr1 knock-out (KO) mice, a model of Fragile-X Syndrome, to test the E/I imbalance theory." (PMID 29019321, 2017). "Fragile-X syndrome (FXS) patients display intellectual disability and autism spectrum disorder due to silencing of the X-linked, fragile-X mental retardation-1 (FMR1) gene." (PMID 29116166, 2017). "Fragile X syndrome (FXS) is such a kind of inherited disease characterized by intellectual disability and caused by Fmr1 gene deletion or mutation, even though the mechanism is still under debate." (PMID 28931651, 2017). "Inhibitors of histone deacetylases are very weak reactivators of the FMR1 gene in Fragile X syndrome cell lines." (PMID 29209628, 2017). "The differential neuronal activation patterns and differential gene expression patterns elicited by a novel social stimulus did intersect with reported neuroimaging findings in fragile X syndrome as well as previous molecular findings in the Fmr1 null mouse." (PMID 28649315, 2017).